DGCR8 (DGCR8 microprocessor complex subunit)
Diseases named in the same sentence as DGCR8 in open-access papers (continued):
Sharing a sentence is not in itself a finding about the gene and the disease.
DiGeorge syndrome (26 papers, 2009 to 2026). "Previous studies reported that human pri-miR-9-2 is efficiently processed in a DGCR8-dependent manner in 22q11.2 deletion syndrome model mice and Dgcr8-deficient mice." (PMID 33581109, 2021). "Deletion of DGCR8 causes DiGeorge syndrome, also known as 22q11.2 deletion syndrome, the symptoms of which include hypokalemia (due to hypoparathyroidism), immune dysfunction (due to thymic hypoplasia) and congenital heart disease." (PMID 26308063, 2015). "DGCR8 deficiency in the brain has also been suggested to cause behavioral and neuronal defects associated with the 22q11.2 deletion syndrome known as DiGeorge syndrome." (PMID 24239349, 2013). "The discovery of the relationships between the locus encoding DGCR8 protein and the miRNA processing suggested that one of the main causes of DiGeorge syndrome is an impairment in miRNA biogenesis." (PMID 22949860, 2012). "In humans, the loss of one functional allele of DGCR8 is sufficient to impair miRNA production, suggesting to be the cause of the physiological defects seen in 22q11.2 deletion syndrome, including pluripotency defects, immunodeficiency due to an underdeveloped thymus, and psychiatric illnesses." (PMID 41403701, 2025). "22q11.2 deletion syndrome (22q11DS), also known as DiGeorge Syndrome, is caused by hemizygous microdeletion of a region on chromosome 22 that encodes the Microprocessor component DGCR8." (PMID 30618607, 2018). "Interestingly, deletions in the chromosome 22 that affect the gene encoding DGCR8 protein are the cause of the DiGeorge syndrome and have been well known since the early 80s." (PMID 22949860, 2012). "Recently, Dgcr8 gene has also gained momentum in the physiopathology of neural defects observed in the DiGeorge syndrome, a genetic disorder that in humans originates from the micro deletion of the region q11.2 of chromosome 22 encoding for about 30 genes, including the DGCR8 gene." (PMID 24519472, 2014). "In a human cellular model system of DiGeorge syndrome, cortical neurons derived from DGCR8 +/− hiPSCs showed defective neuronal activity and calcium handling, which were in line with the results of the mouse models." (PMID 36360162, 2022). "Several RNA-binding proteins, including DGCR8, function in pri-miRNA processing and are involved in neuronal development and diseases such as DiGeorge syndrome." (PMID 33581109, 2021). "Hemizygous microdeletions in the 22q11.2 region, CNVs which include the DGCR8 gene, lead to an ~20- to 25-fold increase in SCZ risk, and studies in animal models of 22q11.2 deletion syndrome (22q11DS) report widespread deficits in brain miRNA levels." (PMID 34685659, 2021). "The DGCR8 gene is heterozygously deleted along with about 30 other genes in DiGeorge syndrome patients." (PMID 22768307, 2012). "Dgcr8+/− mouse models indicated pri-miRNA processing defects in the brain and neurological defects and symptoms similar to those observed in DiGeorge syndrome." (PMID 22768307, 2012). "The DGCR8 gene, which maps to chromosomal region 22q11.2, is commonly deleted in DiGeorge syndrome, characterized by cardiovascular defects, craniofacial defects, immunodeficiency and neurobehavioral alterations." (PMID 19889204, 2009). "Interestingly, Dgcr8 haploinsufficiency contributes to neurological, behavioral, and anatomical phenotypes of the 22q11 Deletion Syndrome (22q11DS), that encompasses DiGeorge syndrome, velo-cardio-facial syndrome and conotruncal anomaly face syndrome." (PMID 37213213, 2023). "In a human cellular model system of DiGeorge syndrome, cortical neurons derived from DGCR8 +/− hiPSCs show defected neuronal activity and calcium handling, and the monoallelic mutant cells have altered resting membrane potential and abnormal inactivation of voltage-gated calcium channels." (PMID 36360162, 2022).
DiGeorge syndrome (continued). "Originally described in Drosophila, Drosha and Pasha (the vertebrate ortholog of Pasha is called DGCR8—DiGeorge syndrome chromosomal region) are the key proteins of the microprocessor complex, which is involved in the initiation of miRNAs processing in the nucleus." (PMID 33334059, 2020). "In the nucleus, these pri-miRNAs are processed by RNase III Drosha and the DiGeorge syndrome chromosomal region 8, Microprocessor Complex Subunit (DGCR8; DiGeorge syndrome chromosomal region 8) protein, generating a precursor miRNA (pre-miRNA) of approximately 100 bp." (PMID 29190882, 2017). "Deletion of DGCR8 induces DiGeorge syndrome (22q.2 deletion syndrome)." (PMID 26308063, 2015). "DGCR2, DGCR8, and UFD1 are deleted in individuals with 22q11.2 deletion syndrome (22q11DS), which occurs in individuals who have increased susceptibility for psychiatric disorders." (PMID 30923314, 2019).
breast carcinoma (15 papers, 2012 to 2025). "A DGCR8 SNP, rs9606250 (A > T) is strongly linked to poor disease-free survival (HR = 0.21; CI 0.05–0.84) in Korean breast cancer patients." (PMID 30897768, 2019). "These PAK5-mediated modifications consequently increase oncogenic miR-10b biogenesis by augmenting the interaction of DDX5 with the Drosha-DGCR8 complex, facilitating pri-miR-10b cleavage and maturation in breast cancer." (PMID 38689093, 2024). "DGCR8 acts as an oncogene and participates in the tumorigenesis and progress of several cancers, such as breast cancer, ovarian cancer and GBM." (PMID 35945192, 2022). "To validate the association between DGCR8 and USP51 in patients with breast cancer, we immunohistochemically stained these two proteins in breast tumors (n = 139) from patients with a long-term (~12 years) follow-up record." (PMID 34188037, 2021). "In line with previous findings, down-regulation of DDX5, DDX17, and DGCR8 transcript levels in breast cancer was observed." (PMID 34117091, 2021). "Collectively, these findings indicate that DGCR8 promotes the radioresistance of breast cancer cells in vitro and in vivo independently of Drosha binding." (PMID 34188037, 2021). "Next, we examined how the expression levels of DDX5, DDX17, and DGCR8 genes correlate with breast cancer patients’ survival." (PMID 34117091, 2021). "To assess the clinical relevance of DGCR8 expression to radiotherapy in patients, we analyzed a cohort of human breast cancer patients in which transcriptomic profiling was obtained from 286 tumor samples; 87% of these patients had received radiotherapy." (PMID 34188037, 2021). "Dysregulation of DROSHA and DGCR8 has been observed in many cancers such as epithelial skin cancer, breast cancer and ovarian cancer." (PMID 27957388, 2016). "The possible role of DGCR8 gene in the clinical outcome of breast cancer has been recently reported." (PMID 22639842, 2012). "It was shown that impaired miRNA processing through knockdown of DGCR8 facilitates breast cancer cell invasion." (PMID 22639842, 2012). "In contrast, it was reported that DDX5 is involved in TGF-β (transforming growth factor-β)- and BMP (bone morphogenic protein)-specific SMAD signaling-induced oncogenic miR-21 maturation by forming a protein complex with Drosha-DGCR8 in breast cancer cells 166,167." (PMID 38689093, 2024). "This promotes DDX5/Drosha/DGCR8 complex formation and miR-10b processing in breast cancer." (PMID 37762595, 2023). "Furthermore, Kaplan–Meier analysis showed that high levels of DGCR8 (log-rank P = 2 × 10−10) and USP51 (log-rank P = 0.0001) were significantly associated with poor overall survival after surgery in patients with breast cancer." (PMID 34188037, 2021). "This could reconcile the discrepancy observed between the tumor-suppressive nature of DGCR8 and the oncogenic property of Drosha in breast cancer, suggesting that Drosha might be involved in other cellular complexes and functions as well." (PMID 34117091, 2021). "Recently, DGCR8 was reported to increase miR-27b in ovarian and breast cancer cells." (PMID 26910911, 2016). "Importantly, our in vitro and mouse preclinical findings are supported by human clinical data where increased expression of WAVE2 and ITGB1, and decreased expression levels of miR-29 and DGCR8 correlate with poor disease outcome in human patients with breast cancer tumors." (PMID 36968231, 2023). "In addition, under irradiation, miR-27a-3p mimics induced marked death of HNSCC cells in the colony formation assay, which suggested that miR-27a-3p improved the radiosensitivity of HNSCC cells DGCR8 as an oncogene is upregulated in breast cancer, ovarian cancer and glioma." (PMID 34389030, 2021). "Combined DDX5/DDX17/DGCR8 expression profiles as a signature showed a stronger effect, HR = 0.47 (95% CI: 0.4-0.55, logrank P-value = 1 × 1016), meaning that lower expression of this set of signature genes correlated with ∼2 times increase in the survival of breast cancer patients." (PMID 34117091, 2021).
breast carcinoma (continued). "The analyses revealed that the key components of microprocessor complex such as DGCR8, DDX5, and DDX17 are down-regulated in breast cancer as compared with the healthy samples." (PMID 34117091, 2021). "Owing to the diverse range of uncommon functions of DGCR8 and Drosha in the cell, targeting the whole microprocessor complex via silencing all the components could better clarify the overall oncogenic or tumor-suppressive nature of this complex in the context of breast cancer." (PMID 34117091, 2021). "To examine the association between the key miRNA biogenesis proteins and radioresistance, we stably expressed Drosha, DGCR8, Exportin-5, or Dicer in LM2 cells, a lung-metastatic subline of MDA-MB-231 human breast cancer cells." (PMID 34188037, 2021). "In breast cancer, the nucleolin (NCL) protein directly interacts with the DGCR8 and Drosha microprocessor complex in the nucleus to affect the biogenesis of miR-15a/16 at the primary to precursor stage of processing." (PMID 31766744, 2019). "We identified a strong positive link between Δsv-MALAT1 overexpression and DGCR8 expression, suggesting that Drosha-DGCR8 complex (Microprocessor) controlled the abundance of Δsv-MALAT1 in breast cancer as in HEK 293T cells." (PMID 27172249, 2016). "Although WBP2 did not regulate the expression level of the microprocessor complex components, that is, DGCR8, Drosha, DDX5, and DDX17, it suppressed the activity of pri-miRNA–processing machinery via physical interactions with these components in breast cancer." (PMID 34117091, 2021).
bladder cancer (14 papers, 2017 to 2025). "A recent study assessed the association between METTL3 and DGCR8 in a bladder cancer model." (PMID 32209098, 2020). "METTL3 also enhances the binding of pri-miR-221/222 to DGCR8 to regulate bladder cancer proliferation." (PMID 36226036, 2022). "METTL3 can actively regulate pri-miR221/222 in an m6A-dependent manner by interacting with DGCR8, a micro-processor protein that promotes the processing of pri-miR221/222 into mature miR221/222 in bladder cancer." (PMID 32765970, 2020). "In the present study, we found that METTL3 was required for the engagement of pri-miRNAs by the DGCR8 in bladder cancer." (PMID 31228940, 2019). "In the present study, we indeed found METTL3 exhibited its oncogenic role in bladder cancer through interacting with the microprocessor protein DGCR8 and positively modulating the pri-miR221/222 process in an m6A-dependent manner." (PMID 31228940, 2019). "The SNPs in the DGCR8 gene (rs2073778 and rs720012) are associated with the risk of progression and the muscle invasion of NMIBC, suggesting that the malfunction of DGCR8 also shows its special clinical significance in bladder cancer." (PMID 28187437, 2017). "We only know that DGCR8 is also over-expressed in bladder cancer tumour tissues, but it is downregulated in the normal urothelia of patients with bladder cancer." (PMID 28187437, 2017). "In bladder cancer cells, METTL3 can interact with DGCR8 and positively regulate the pri-miR-221/222 synthesis in an m6A-based pathway, which might provide new insight on bladder cancer therapy and therapy resistance." (PMID 32122355, 2020). "All these results implied that METTL3 could affect pri-miRNAs processing by regulating the recognition and binding of DGCR8 to pri-miRNAs in bladder cancer." (PMID 31228940, 2019). "Our findings suggested that METTL3 may have an oncogenic role in bladder cancer through interacting with the microprocessor protein DGCR8 and positively modulating the pri-miR221/222 process in an m6A-dependent manner." (PMID 31228940, 2019). "Notably, METTL3 functions as An oncogenic driver in bladder cancer by engaging in a functional interaction with DiGeorge syndrome critical region gene 8 (DGCR8), thereby enhancing the biogenesis of miR-221/222 through positive regulation of pri-miR221/222 processing." (PMID 40986143, 2025). "In bladder cancer and cardiac hypertrophy models, METTL3 exerts oncogenic and pro-fibrotic effects by facilitating DGCR8-mediated maturation of pri-miR-221/222 in an m6A-dependent manner." (PMID 40547022, 2025). "In bladder cancer, METTL3 interacts with DGCR8, and actively promotes the maturation of pri-miR-221/222 in a m6A dependent manner, further reduces the expression of PTEN and promotes the proliferation of bladder cancer." (PMID 35022030, 2022). "And we demonstrated that METTL3 could downregulate PTEN expression by interacting with the microprocessor protein DGCR8 and positively modulating the pri-miR221/222 process in an m6A-dependent manner, which may provide a prognostic and/or therapeutically target for the treatment of bladder cancer." (PMID 31228940, 2019). "By binding to the processor protein DGCR8 and favorably controlling the pri-miR222/6 pathway in a m221A-dependent manner, METTL3 (methyltransferase-like 3) may play an oncogenic function in bladder cancer." (PMID 38329551, 2024).
hepatocellular carcinoma (12 papers, 2017 to 2025). A malignant tumor that arises from hepatocytes. "In human hepatoma cells (HCC), decreased m6A and METTL14 was detected and overexpression of METTL14 can interact with DGCR8 to regulate the maturation of pri-miRNA126 in an m6A-dependent manner, reducing the metastasis of hepatoma cells." (PMID 32898471, 2020). "Mechanistically, RNA immunoprecipitation assays showed that the microprocessor Drosha or DGCR8 interacted with HMGA2 mRNA in hepatoma cells." (PMID 28522832, 2017). "Studies discovered that m6A methylase METTL14 could regulate pri-miRNA processing by directly targeting DGCR8 in a way dependent on METTL14/m6A in hepatocellular carcinoma." (PMID 35733918, 2022). "In addition, METTL14 was identified to interact with DGCR8 and regulate the pri‐miR‐126 mature process in an m6A‐dependent manner in hepatocellular carcinoma." (PMID 32808488, 2020). "Studies have shown that METTL14 promotes pri-miR-126 maturation through the recruitment of DGCR8-dependent m6A in hepatocellular carcinoma (HCC)." (PMID 40734692, 2025). "METTL14 interacts with DGCR8 to modulate pri-miR-126 and suppresses the metastatic potential of hepatocellular carcinoma (HCC)." (PMID 31142332, 2019). "As a suppressor in hepatocellular carcinoma (HCC), METTL14 interacts with DGCR8 to promote the processing of pri-miR-126 via an m6A-dependent pattern, triggering the enhanced level of miR-126 which represses the tumor metastasis." (PMID 33754077, 2021). "In hepatocellular carcinoma (HCC), METTL14 binds DGCR8 and facilitates m6A-dependent processing of pri-miR-126." (PMID 41301491, 2025). "In hepatocellular carcinoma (HCC), METTL-14 can also interact with DGCR8." (PMID 36553003, 2022).
Wilms tumor (11 papers, 2015 to 2025). An embryonal neoplasm characterized by the presence of epithelial, mesenchymal, and blastema components. "Other mutations like somatic as well as germline mutations in DGCR8 have also been observed in Wilms tumors." (PMID 34721577, 2021). "DGCR8 is also associated with susceptibility to various cancers, including prostate cancer, Wilms tumor, and ovarian cancer." (PMID 34257547, 2021). "A “hot-spot” in the first double-strand RNA (dsRNA) binding domain (dsRBDe) of DGCR8 is the missense mutation of E518K, which contributes to over 70% of the DGCR8 mutations in Wilms tumors." (PMID 34721577, 2021). "DGCR8 is frequently mutated in Wilms tumors, and the recurrent mutation of E518K in the dsRBD1 domain of DGCR8 results in the decrease of miRNAs, implicating the importance in controlling the pri-miRNA processing machinery in cancer pathogenesis." (PMID 32138313, 2020). "Together with the mutations in SIX1/2, mutations of DGCR8 and Drosha are associated with Wilms tumor." (PMID 26308063, 2015). "Previous studies reported that the biallelic alteration in DGCR8—the E518K missense mutation accompanied by LOH where the WT allele localizes—seems to be present not only in thyroid tumors, but also in Wilms’ tumors, schwannomatosis, and pineoblastomas." (PMID 38607000, 2024). "In Wilms’ tumors and pineoblastoma, somatic mutations in miRNA biogenesis genes (DROSHA, DGCR8, DICER1) or in genes involved in the degradation of miRNA (DIS3L2) have also been reported." (PMID 38607000, 2024). "Most recently, two study groups showed that mutations in DGCR8, Drosha, together with mutations in SIX1/2, are associated with blastemal type Wilms tumors (WT)." (PMID 26308063, 2015). "Mutations in DGCR8 are observed in thyroid cancer, and mutations in both DROSHA and DGCR8 occur in Wilms’ tumor, highlighting the importance of maintaining Microprocessor integrity." (PMID 41403701, 2025). "With exception of hotspot mutations found in DICER1, we found only a few mutations in other miRNA biogenesis genes, i.e. DROSHA, DGCR8 and XPO5, which have been recently observed in different childhood cancers associated with DICER1 syndrome and in Wilms' tumor." (PMID 33406242, 2021). "Moreover, mutations in typical Wilms tumour genes were identified, such as WT1, DIS3L2, WTX, CTNNB1 and the miRNA-processing genes DROSHA, DGCR8 and DICER1." (PMID 32161258, 2020). "Additionally, the specific hotspot mutations in DROSHA and DGCR8 commonly observed in Wilms' tumor and other childhood cancers were absent in adult cancers." (PMID 33406242, 2021).
glioma (8 papers, 2020 to 2022). A benign or malignant brain and spinal cord tumor that arises from glial cells (astrocytes, oligodendrocytes, ependymal cells). "Recent studies have shown that STAT5A can promote the transcription of LINC01198, which promotes the proliferation of glioma cells by stabilizing DGCR8." (PMID 34276757, 2021). "In summary, the data we showed here suggested that STAT5 induced LINC01198 promotes proliferation and motility of glioma cells through stabilizing DGCR8 in glioma cells." (PMID 32246817, 2020). "Inspired by these previous studies, we next sought to investigate the differential miRNA profile involved in the alteration of DGCR8 expression in glioma cells of our own." (PMID 32246817, 2020). "In our study, the biological roles as well as clinicopathological significance of DGCR8 expression in glioma remains unknown, which left to be investigated." (PMID 32246817, 2020). "Besides, it was reported that LINC01198 could maintain the stability of DGCR8 and promotes the proliferation of glioma cells." (PMID 35945192, 2022). "Given the key role of DGCR8 mediated in the microprocess and biogenesis of miRNA involved in carcinogenesis, we next wonder whether the miRNA profile could be mediated by DGCR8 in glioma." (PMID 32246817, 2020). "By stabilizing DGCR8, STAT5 can induce LINC01198 to promote glioma cell proliferation and motility of glioma cells." (PMID 35517418, 2022). "DGCR8 was also reported to decrease lncRNA ZFAT-AS1 expression by attenuating its stability to induce its cleavage and promote the malignant biological behavior of glioma." (PMID 35945192, 2022). "Moreover, RBP DGCR8 could bind with ZFAT-AS1, the interaction between DGCR8/ZFAT-AS1 and CDX2 contributed to the malignant progression of glioma." (PMID 34178684, 2021).